CFTR (CF transmembrane conductance regulator)
Diseases named in the same sentence as CFTR in open-access papers (continued):
Sharing a sentence is not in itself a finding about the gene and the disease.
cystic fibrosis (continued). "The Cystic Fibrosis is an autosomal recessive disease caused by mutations in CFTR gene, resulting in alteration of the chloride channel activity." (PMID 32234058, 2020). "ORKAMBI® (Lumacaftor-Ivacaftor) is an approved combination therapy for Cystic Fibrosis patients bearing the most common mutation, F508del, in the cystic fibrosis conductance regulator (CFTR) protein." (PMID 32092967, 2020). "However, since the offspring of these couples is at risk of cystic fibrosis when the female partner is heterozygous for the CFTR gene, screening for this mutation is imperative in humans before attempting assisted reproduction technology procedures (Field & Martin, 2011; Tüttelmann & Simoni, 2008)." (PMID 32293822, 2020). "Although rare, mutation-mediated CFTR dysfunction is implicated in the dysregulation of glucose metabolism, impairment of insulin release, complications in lung and airway and subsequent multiorgan failure, which contribute to the high mortality of cystic fibrosis." (PMID 32724454, 2020). "CF is caused by mutations in the Cystic Fibrosis Transmembrane Conductance Regulator (CFTR) gene, which encodes an anion channel expressed in the apical membrane of epithelial cells." (PMID 32204475, 2020). "CF is an autosomal recessive genetic disease associated with a 250,000 base-pair region on chromosome 7q encoding cystic fibrosis transmembrane conductance regulator (CFTR)." (PMID 32454915, 2020). "Cystic fibrosis is an autosomal recessive disease caused by mutations in the cystic fibrosis transmembrane conductance regulator (CFTR) gene (1, –3)." (PMID 31882447, 2020). "In cystic fibrosis, one of the most frequent genetic diseases, loss of function of CFTR disrupts mucociliary clearance and innate defense mechanisms resulting in airway obstruction by mucus accumulation and bacterial colonization." (PMID 32933106, 2020). "Different mutations involving the cystic fibrosis transmembrane regulator protein (CFTR) gene, which encodes the CFTR channel, are involved in CF." (PMID 33138251, 2020). "Cystic fibrosis is an autosomal recessive disease caused by a mutation in the CFTR protein that regulates ion transport across epithelia." (PMID 33028687, 2020). "Cystic fibrosis is a common autosomal recessive disorder caused by mutations in the cystic fibrosis transmembrane conductance regulator (CFTR) gene." (PMID 32560275, 2020). "A substantial fraction of cystic fibrosis cases, a chronic disease affecting the lungs and the digestive system, is due to nonsense mutations in the CFTR gene." (PMID 32575694, 2020). "Cystic Fibrosis is a life-limiting genetic disease caused by mutations to the Cystic Fibrosis Transmembrane Regulator (CFTR) gene." (PMID 33505366, 2020). "CF is caused by mutations in the ABCC7 gene encoding the Cystic Fibrosis Transmembrane conductance Regulator (CFTR), a transmembrane channel that has a critical role in regulating transepithelial movement of water and electrolyte in epithelial cells." (PMID 32144307, 2020). "CF is caused by mutations in the cystic fibrosis transmembrane conductor regulatory (CFTR) gene, which plays critical functions in epithelial ion transport and hydration of mucus." (PMID 31992345, 2020). "Cystic fibrosis is a genetic, multi-organ disease that results from loss in function of the CF transmembrane conductance regulator (CFTR)-anion channel." (PMID 32680508, 2020). "Cystic Fibrosis is a lethal recessive disease caused by loss-of-function mutations in the CFTR (cystic fibrosis transmembrane conductance regulator)." (PMID 32331485, 2020). "CF is a monogenic disease resulting from mutations within the cystic fibrosis transmembrane conductance regulator (CFTR) on chromosome 7 currently comprising >2000 different mutations." (PMID 33202578, 2020).
cystic fibrosis (continued). "Cystic fibrosis is an autosomal recessive disease, caused by mutations in the gene encoding the cystic fibrosis transmembrane conductance regulator (CFTR) anion channel, resulting in altered chloride ion (Cl-) transport." (PMID 33391268, 2020). "CFTR mutations cause cystic fibrosis, an airway disease that phenotypically resembles COPD and is characterized by chronic bronchitis." (PMID 32992527, 2020). "CF, a common autosomal recessive disease that affects mainly the lungs, is primarily driven by cystic fibrosis transmembrane conductance regulator (CFTR) mutation." (PMID 32802893, 2020). "CF is caused by mutations in the cystic fibrosis transmembrane conductance regulator (CFTR), which codes for a protein that functions as a chloride ion transporter." (PMID 32733828, 2020). "Cystic fibrosis is an inherited disorder which is caused due to a mutation in the cystic fibrosis transmembrane conductance regulator (CFTR) gene." (PMID 32313785, 2020). "In 1989, the discovery that mutations cause CF in the cystic fibrosis transmembrane conductance regulator (CFTR) gene, which leads to abnormal ion transport in mucous membranes throughout the body." (PMID 33103563, 2020). "CF is a genetic disease where the cystic fibrosis transmembrane conductance regulator (CFTR) gene is mutated." (PMID 32153575, 2020). "Thus, with cystic fibrosis, defects in CFTR also impose a loss of ENaC activity." (PMID 32124007, 2020). "Cystic fibrosis is an autosomal disease caused by mutations in the cystic fibrosis transmembrane conductance regulator (CFTR) gene." (PMID 33060788, 2020). "Cystic fibrosis is a genetic disorder caused by mutations (deletion of phenylalanine from the position-508—F508del is the most common) in the cystic fibrosis transmembrane conductance regulator (CFTR) gene, a membrane ion channel primarily regulating chloride efflux." (PMID 32927853, 2020). "This disease is caused by defects in CF genes, the so-called mutations in cystic fibrosis transmembrane conductance regulator (CFTR) gene population." (PMID 32234058, 2020). "Cystic fibrosis is an autosomal recessive disease resulting from mutations in the cystic fibrosis transmembrane conductance regulator (CFTR) gene that causes the encoded anion channel to be dysfunctional." (PMID 33038073, 2020). "Cystic Fibrosis is an autosomal recessive pleiotropic disorder caused by mutations in the gene encoding the CF transmembrane conductance regulator (CFTR) chloride channel." (PMID 32765284, 2020). "CF (ICD-10 code E84) is caused by mutations affecting the cystic fibrosis transmembrane conductance regulator (CFTR) protein, which transports chloride ions across epithelial cell membranes." (PMID 32374269, 2020). "Additionally, the high prevalence of CFTR mutations for cystic fibrosis in our population and the severity of this disease make it important to detect couples who may be CFTR carriers and therefore, prevent the birth of a child affected by severe phenotypes." (PMID 32155011, 2020). "CF arises from mutations in the cystic fibrosis transmembrane conductance regulator (CFTR) gene, which expresses an apically localized anion channel in epithelial tissues." (PMID 33396210, 2020). "Mutations of CFTR such as ΔF508 result in Cystic Fibrosis causing a wide range of symptoms linked to a defect in fluid transport across the epithelial membranes." (PMID 33117152, 2020). "CF is an inherited autosomal recessive disorder characterised by mutations in the cystic fibrosis transmembrane conductance regulator (CFTR) gene located on chromosome 7 that primarily affects the lungs." (PMID 33027987, 2020). "Cystic Fibrosis is a recessive genetic disease due to mutations of the Cystic Fibrosis Transmembrane Conductance Regulator (CFTR) gene encoding the CFTR chloride channel." (PMID 32982730, 2020). "Cystic fibrosis is a rare genetic disease caused by mutations in the CF transmembrane conductance regulator (CFTR) chloride channel gene." (PMID 33198319, 2020).
cystic fibrosis (continued). "This disease is caused by a defect in cystic fibrosis genes, the so-called mutations in cystic fibrosis transmembrane conductance regulator (CFTR) gene population." (PMID 32092880, 2020). "Cystic fibrosis is a hereditary disease associated with different classes of mutations in the Cystic Fibrosis Transmembrane conductance Regulator (CFTR), a chloride/carbonate channel." (PMID 32781626, 2020). "Cystic fibrosis is an autosomal recessive genetic disorder caused by disease-causing variants in the CF transmembrane conductance regulator (CFTR) gene." (PMID 32485957, 2020). "Loss of CFTR function causes cystic fibrosis, a fatal autosomal recessive disorder with a disease frequency of 1 in 2,000 live births and a carrier rate of approximately 5% in the Caucasian population." (PMID 33552140, 2020). "Unsurprisingly, patients with cystic fibrosis, which is an inherited disease caused by mutations in the CFTR gene, are characterised by a generalised systemic deficiency in extracellular glutathione and major lung function pathology." (PMID 33266084, 2020). "CF is a recessive monogenic disease due to mutations in the Cystic Fibrosis Transmembrane conductance Regulator (CFTR) gene." (PMID 32982730, 2020). "Chloride ion channel function has also been associated with CRC development, the most notable being the cystic fibrosis transmembrane conductance regulator CFTR in which CFTR gene mutations are associated with causing cystic fibrosis." (PMID 33363037, 2020). "CF is caused by cystic fibrosis transmembrane conductance regulator (CFTR) dysfunction and usually presents with respiratory or digestive symptoms." (PMID 33160331, 2020). "Patients with CF have mutations in the gene encoding cystic fibrosis transmembrane conductance regulator (CFTR), leading to inhibition of Cl– and HCO3– transport by airway and submucosal gland epithelial cells." (PMID 32292784, 2020). "Cystic fibrosis is an autosomal recessive genetic disease caused by mutations in the cystic fibrosis transmembrane conductance regulator (CFTR) chloride channel." (PMID 32459504, 2020). "Cystic fibrosis is an autosomal recessive disorder due to mutations occurring in the CFTR (CF Transmembrane Conductance Regulator) gene, encoding for a chloride-conducting channel located at the apical membrane of epithelial cells." (PMID 32244302, 2020). "Cystic fibrosis is a monogenic autosomal recessive disorder caused by mutations in the Cystic Fibrosis Transmembrane Conductance Regulator (CFTR) gene which encodes a chloride/bicarbonate channel expressed on the apical surface of secretory cells." (PMID 31117296, 2019). "The leading cause of cystic fibrosis is the deletion of phenylalanine 508 (F508del) in the first nucleotide-binding domain (NBD1) of the cystic fibrosis transmembrane conductance regulator (CFTR)." (PMID 31201318, 2019). "Cystic fibrosis is an autosomal recessive disorder caused by genetic mutations in CF transmembrane conductance regulator (CFTR) protein." (PMID 31507425, 2019). "CF is a life-threatening rare autosomal recessive disorder caused by mutations in the Cystic Fibrosis Transmembrane Conductance Regulator (CFTR) gene." (PMID 31921856, 2019). "Cystic fibrosis is a genetic disease involving a mutation in the CF transmembrane conductance regulator (CFTR) gene which results in accumulation of viscous secretions affecting primarily the respiratory and digestive systems." (PMID 31318914, 2019). "A widely studied example for such a failure is the folding and trafficking problem of the ABCC7 protein (cystic fibrosis transmembrane conductance regulator, CFTR) caused by the most frequent mutations in the disease, cystic fibrosis." (PMID 31597297, 2019). "Cystic fibrosis is a recessive autosomal disease, caused by mutations of the Cystic Fibrosis Transmembrane Conductance Regulator (CFTR) gene." (PMID 30889905, 2019).
cystic fibrosis (continued). "Cystic fibrosis is caused by mutations in the gene encoding the cystic fibrosis transmembrane conductance regulator (CFTR) protein that resides at the apical surface of many epithelial cell types." (PMID 31396394, 2019). "Cystic Fibrosis is a recessive genetic disorder caused by mutations in the cystic fibrosis transmembrane conductance regulator (CFTR)." (PMID 31428093, 2019). "The diagnosis of cystic fibrosis is commonly confirmed by molecular genetics with the presence of specific mutations of cystic fibrosis transmembrane conductance regulator (CFTR) gene." (PMID 31187952, 2019). "We report a case of cystic fibrosis in a 15-year-old female patient who is a compound heterozygote for CFTR gene, with delta F508 and Tyr109Glyfs mutations detected." (PMID 31187952, 2019). "CF is a monogenic disorder caused by mutations in the Cystic Fibrosis Transmembrane conductance Regulator (CFTR)." (PMID 31551982, 2019). "Familial loss-of-function mutations of the gene coding for the cystic fibrosis transmembrane conductance regulator (CFTR) channel protein cause cystic fibrosis, the most frequent inherited life-threatening disease in the Caucasian population." (PMID 30898172, 2019). "The cystic fibrosis transmembrane conductance regulator (CFTR) gene has been identified as a causative gene for cystic fibrosis 5 and is also reported to be a gene associated with pancreatitis." (PMID 30992994, 2019). "Cystic fibrosis is a genetic disorder caused by mutations in the cystic fibrosis transmembrane conductance regulator (CFTR) gene, and is characterized by the retention of thick airway secretions and chronic pulmonary infections." (PMID 30781366, 2019). "Cystic fibrosis is a life–threatening lung disease caused by a loss-of-function mutation of cystic fibrosis transmembrane conductance regulator (CFTR, F508del)." (PMID 30717487, 2019). "The fundamental cause of CF is the recessive mutations in the Cystic Fibrosis Transmembrane Conductance Regulator (CFTR) gene, which encodes a chloride/bicarbonate (Cl− and HCO3−) anion channel." (PMID 30813645, 2019). "CF is an inherited disease caused by mutations in the cystic fibrosis transmembrane conductance regulator (CFTR) gene." (PMID 30764828, 2019). "Cystic fibrosis is an autosomal recessive hereditary disorder resulting from mutations in the cystic fibrosis trans-membrane conductance regulator (CFTR) gene." (PMID 30781363, 2019). "CF is a channelopathy, where a genetic mutation to the cystic fibrosis transmembrane conductance regulator (CFTR) protein results in a malfunctioning chloride channel." (PMID 30986928, 2019). "Cystic fibrosis is an autosomal recessive genetic disease due to mutations in the cystic fibrosis conductance regulator (CFTR) gene." (PMID 30813620, 2019). "Cystic Fibrosis is a monogenic disease caused by mutations in the cystic fibrosis transmembrane conductance regulator (CFTR) gene, resulting in defective CFTR-mediated chloride and bicarbonate transport, with dysregulation of epithelial sodium channels (ENaC)." (PMID 31532390, 2019). "Cystic fibrosis is a disease caused by loss-of-function mutations affecting the CF transmembrane conductance regulator (CFTR), a chloride channel." (PMID 30737369, 2019). "In cystic fibrosis, mutations in the cystic fibrosis transmembrane conductance regulator (CFTR) gene disrupt the capacity of the encoded protein to function as a channel to transport chloride ions and water across cell membranes." (PMID 30813620, 2019). "In patients with cystic fibrosis, the CFTR mutation causes the disruption of Na+, K+, Cl−, HCO3−, and water transport in exocrine ducts of the salivary glands." (PMID 31847106, 2019). "Cystic fibrosis is a frequent autosomal recessive disorder induced by mutations in the cystic fibrosis transmembrane conductance regulator (CFTR) gene, which encodes a cyclic adenosine monophosphate (cAMP)-dependent chloride channel." (PMID 31871532, 2019).
cystic fibrosis (continued). "The treatment benefit of ivacaftor (IVA) in patients with CF with a G551D mutation in the cystic fibrosis transmembrane conductance regulator (CFTR) gene has been established in Phase 3 studies." (PMID 31409396, 2019). "Despite the continued development of cystic fibrosis transmembrane conductance regulator (CFTR) modulator drugs for the treatment of cystic fibrosis, the need for mutation agnostic treatments remains." (PMID 30875857, 2019). "This homeostatic function is compromised in cystic fibrosis due to loss-of-function mutations in the CF transmembrane conductance regulator (CFTR)." (PMID 30874543, 2019). "Over 2000 pathogenic variants have been detected which cause a defect in CFTR (cystic fibrosis transmembrane conductance regulator) protein synthesis and/or function but only a few hundred are pathogenic variants as underlying reason for CF disease." (PMID 30975115, 2019). "Cystic fibrosis, resulting from a mutation of the Cystic fibrosis transmembrane conductance regulator (CFTR) gene, is the most common inherited disease in Caucasians affecting over 70,000 people worldwide." (PMID 31555243, 2019). "The cystic fibrosis transmembrane conductance regulator (CFTR) chloride channel is dysfunctional in CF, leading to a loss of fluid secretion and probably impaired bicarbonate transport, along with Na+ hyperabsorption." (PMID 30761000, 2019). "CF patients carry mutations in the gene for the cystic fibrosis transmembrane conductance regulator (CFTR), an ion channel managing the passage of chloride and bicarbonate ions across the apical membrane of epithelial cells." (PMID 30717260, 2019). "CF is a genetic disorder caused by a mutation in the cystic fibrosis transmembrane conductance regulator (CFTR) gene that affects the lungs, as well as the pancreas, liver, kidneys and intestine." (PMID 30909579, 2019). "Cystic fibrosis is a genetic condition caused by dysfunction of the cystic fibrosis transmembrane conductance regulator (CFTR) protein." (PMID 31076617, 2019). "Similarly, cystic fibrosis is caused by recessive inheritance of mutations in CFTR." (PMID 31591409, 2019). "Cystic fibrosis is a hereditary life-limiting disease that is caused by mutations in the gene of the cystic fibrosis transmembrane conductance regulator (CFTR)." (PMID 31699101, 2019). "Cystic fibrosis is a life-limiting, autosomal recessive disease caused by pathogenic mutations in the gene encoding the CF transmembrane conductance regulator (CFTR) protein." (PMID 31640630, 2019). "This systematic review examines the clinical efficacy and safety of CFTR modulators in individuals with cystic fibrosis with specific genetic mutations." (PMID 31076617, 2019). "Cystic fibrosis is a genetic disease caused by a defect of CF transmembrane conductance regulator (CFTR) gene." (PMID 31583102, 2019). "Cystic fibrosis is an autosomal recessive genetic disease resulting from mutations in the cystic fibrosis transmembrane conductance regulator (CFTR) gene." (PMID 31540982, 2019). "CF is caused by mutations in the cystic fibrosis transmembrane conductance regulator (CFTR) chloride channel, which is normally expressed in epithelial cells of many organs." (PMID 31383635, 2019). "The devastating inherited disease cystic fibrosis is caused by mutations of the Cystic Fibrosis Transmembrane Conductance Regulator (CFTR) anion channel." (PMID 31205003, 2019). "Cystic fibrosis is an inherited disorder caused by mutations in the CF transmembrane conductance regulator (CFTR) gene that promotes persistent lung infection and inflammation and progressive loss of lung function." (PMID 31262295, 2019). "In the lung, it plays a key role in hydration and pH regulation of airway secretions and loss-of-function mutations in the CFTR gene are responsible for Cystic Fibrosis, the most common autosomal recessive disease among Caucasians2." (PMID 31551433, 2019).